ZEB1 (zinc finger E-box binding homeobox 1)
Diseases named in the same sentence as ZEB1 in open-access papers (continued):
Sharing a sentence is not in itself a finding about the gene and the disease.
tumor (continued). "As it has been shown that ZEB1/miRNA-200 modulates the level of PD-L1, which suggests that the more mesenchymal-like tumor cells are intrinsically capable of immuno-escape, we extended the immunophenotyping of the immune host compartment to PD-L1." (PMID 28415643, 2017). "Single ZEB1+ cells scatter in the periphery of the tumor and their relative numbers (i.e. the percentage of ZEB1+ cells) increase simultaneously with overall cellularity (blue) when approaching the tumor core (red)." (PMID 28945795, 2017). "Here the authors uncover a double feedback loop between miR-1199-5p and the Zeb1, potentially coordinating a protein involved in epithelial mesenchymal transition and tumour metastasis." (PMID 29079737, 2017). "Although these findings in part explain the molecular downstream function of ZEB1 within the tumor cell, efficient invasion and metastasis require interaction with the extracellular matrix (ECM) and the surrounding stroma as well." (PMID 28086235, 2017). "We determined the percentage of ZEB1+ cells (ZEB1 labelling index) from three cores per tumor with an average of 3,693 nuclei (min." (PMID 28945795, 2017). "In conclusion, we newly determined that miR-133b targeted the HOXA9/ZEB1 pathway to promote tumor metastasis in CRC cells." (PMID 28969042, 2017). "A number of TFs were significantly altered in two or more tumour types, including ZEB1, JUN, ELK1, FOXM1, while others were limited to a single type, such as FOXD1 in HNSC and FOXL1 in KIRC." (PMID 28139702, 2017). "As higher ZEB1 expression has been suggested in migrating tumor cells, we also analyzed the mean staining intensity of each ZEB+ nucleus with respect to location (green)." (PMID 28945795, 2017). "This is also consistent with our PDX data where increasing expression of ZEB1/ZEB2/SNAI1 leads to lower tumor initiating capacity suggesting that a terminal mesenchymal phenotype has the lowest tumor initiating frequency." (PMID 29162812, 2017). "In gross total resections, we rather observed decreasing ZEB1+ percentage when approaching the tumor edge." (PMID 28945795, 2017). "The expression levels of membrane EGFR, and nuclear FAK, Slug and ZEB1 were decreased in the xenograft tumours of CXB-treated mice." (PMID 28740192, 2017). "The aim of our study was to investigate EpCAM‐negative CTCs that were isolated from patients with metastatic breast cancer (mBC) and focus on LKB1 and ZEB1 expression to dissect their functional roles in triggering anoikis and tumor progression." (PMID 28700115, 2017). "Observations in LNCaP and DU145 cells show that ZEB1 mediates the effect of FOXC2 on tumor-initiating potential and drug resistance, traits that are often correlated with EMT." (PMID 29623961, 2017). "We identified HAS2, tumor cell-derived HA and ZEB1 to form a positive feedback loop as ZEB1, elevated by HA, directly activates HAS2 expression." (PMID 28086235, 2017). "Conversely, ZEB1 overexpression in MCF-7 cells resulted in decreased cell sensitivity to tamoxifen in tumor xenografts." (PMID 28383555, 2017). "First, we showed that ZEB1 is required for tumor initiation and expression of stemness markers in vitro and in vivo, and this effect is Ngn3-dependent." (PMID 28903350, 2017). "Loss of E‐cadherin expression during EMT is induced by ZEB1 and ZEB2 enabling tumour cells to dissociate from the tumour mass, invade local tissues and metastasise to distant sites." (PMID 28133913, 2017). "Zinc finger E-box binding Homebox 1 (ZEB1) is a transcriptional repressor which has been shown to promote tumor invasion and metastasis." (PMID 29165393, 2017). "Together with the findings from a report showing the immunosuppressive activity of Ly6G+ PMN‐MDSCs from 4T1 tumor‐bearing mice, these findings suggested that ZEB1 expression in tumor cells increases the PMN‐MDSC population in CD11b+ cells." (PMID 28618162, 2017).
tumor (continued). "We identified the tumor border of a GBM resection sample and quantified cellularity and the relative fraction of ZEB1 positive cells along a radial axis perpendicular to the tumor edge." (PMID 28945795, 2017). "miR205 inhibits epithelial-mesenchymal transition (EMT), by targeting ZEB1/2, and suppresses tumor expansion from basal membrane to stroma." (PMID 29182685, 2017). "A recent study showed that that ZEB1 was detected in invasive regions of colorectal tumors and at the tumor–stroma interface: regions that display reduction in polarity components." (PMID 29258163, 2017). "EMT is a crucial step during tumor cell migration and invasion; ZEB1, E-cadherin and Vimentin have been widely used as classic EMT markers." (PMID 28489585, 2017). "E-cadherin, Zeb1, Vimentin, Snail and Slug have been proven to be a key role in tumor invasion and metastasis." (PMID 27893422, 2017). "EMT is mediated by key transcription factors, including ZEB1, activated by tumor cell interactions with stromal cells and the extracellular matrix (ECM)." (PMID 28086235, 2017). "This was also clinically investigated, with patients treated with docetaxel exhibiting increased ZEB1 tumour expression." (PMID 28133913, 2017). "Next, we evaluated ZEB1 expression by tumor cells near in pseudopalisades and perinecrotic areas from seven additional cases in colabeling with CD68 to discriminate macrophages populating the necrotic region." (PMID 28945795, 2017). "Many of the EMT inducing transcription factors such as Snail1, Snail2/slug, ZEB1, ZEB2, FOXC2 and TWIST1 have been associated with tumor invasion and metastasis." (PMID 29202800, 2017). "Our findings suggested that ZEB1 promotes the proliferation of cancer cells and contributes to the formation of the tumor microenvironment by regulating the expression of inflammatory cytokines." (PMID 28618162, 2017). "Despite structural differences between tumour and control networks, we found a conserved set of associations between miR-200 family members and genes such as VIM, ZEB-1/2 and TWIST-1/2." (PMID 29051564, 2017). "ZEB1 functions as a master regulator of epithelial plasticity in cancer cell invasion and human tumor progression in vivo." (PMID 28786996, 2017). "ZEB1 tumour epithelial nuclear immunolocalisation was assessed for all patients, with ZEB1 stromal staining serving as a positive control." (PMID 28133913, 2017). "Compared with control (Ctrl/231) tumor cells, ZEB1/231 tumor cells displayed a 32.8-fold increase in CSC frequency." (PMID 28903350, 2017). "For epithelial cancers, this has led to a model of tumor progression in which ZEB1 serves as a molecular marker." (PMID 28945795, 2017). "We subsequently examined the molecular mechanism whereby ZEB1 exerted its tumor-promoting effect in EOC in vitro." (PMID 29245917, 2017). "Given the role of ZEB1 in stem cell maintenance, its expression can be used to query the stem cell properties of the tumor and assess the effect of differentiation therapies." (PMID 28246407, 2017). "The ability of c-Myc to regulate EMT or CSC changes likely depends on relative levels of E-cadherin, Zeb1 etc with in the tumor cells." (PMID 28817737, 2017). "Here, we report the identification of miR-1199-5p, as a repressor of EMT, tumour cell invasion and metastasis, which comparable to miR-200 family members targets Zeb1 mRNA for degradation." (PMID 29079737, 2017). "The relationship of this novel CD44s-ZEB1 impacts on cancer cell ability, including increased tumorsphere initiation capacity and tumor metastasis." (PMID 28245823, 2017). "Since E-Cadherin, N-Cadherin, Vimentin, and ZEB1 were considered as potential vital genes implying higher malignancy of tumor cells; Western blot analysis was performed to detect the protein level alteration." (PMID 28903320, 2017). "Vimentin, ZEB1, and Slug genes linked with the EMT process are essential for tumor cells to exhibit survival capacity." (PMID 29038587, 2017).
tumor (continued). "Zeb1-dependent EMT enhances tumor cell responsiveness to the ECM composition and activates FAK/Src pathway signaling by de-repression of the direct miR-200 target, CRKL." (PMID 26728244, 2016). "ZEB1 knockdown led to a significant decrease in tumor growth, confirming the potent anti‐tumor effect of ZEB1 inhibition." (PMID 27596438, 2016). "In summary, we demonstrate for the first time that E-cadherin is a direct hTERT/ZEB1 target in CRC cells and acts as an effector of this signaling pathway to regulate genes associated with tumor invasiveness." (PMID 26540342, 2016). "In this study, by analysing ZEB1-dependent gene expression patterns, we demonstrate mechanistic links explaining the extraordinary potency of ZEB1 in driving tumour progression." (PMID 26876920, 2016). "Xenograft experiments in nude mice were performed with control or ZEB1‐overexpressing A375 cells and revealed a significant increase in tumor growth in the latter case." (PMID 27596438, 2016). "Compared with siRNA-NC group, there was a high-expression of miR-200a-3p, but a low-expression of ZEB1 mRNA in HULC siRNA tumor samples (P<0.01) from the nude mice." (PMID 27285757, 2016). "Our prior proteomic profiling demonstrated that the miR-200/Zeb1 axis simultaneously regulates tumor cell-intrinsic features and the extracellular matrix composition to alter cell-matrix interactions." (PMID 26728244, 2016). "Zinc finger E-box binding homeobox 1 (ZEB1) is an important EMT transcription factor conducting tumor metastasis." (PMID 27036021, 2016). "Our findings highlight the critical ECM-tumor cell interactions regulated by miR-200/Zeb1-dependent EMT that activate intracellular signaling pathways responsible for tumor cell invasion and metastasis." (PMID 26728244, 2016). "Biochemically, the increased matrix responsiveness of tumor cells upon Zeb1 expression was due to enhanced FAK signaling, which was essentially shutoff with high miR-200 levels and phenocopied by CRKL or Itgβ1 knockdown." (PMID 26728244, 2016). "ZEB1 is expressed strongly by infiltrating stroma cells that are found scattered throughout the tumor and most frequently closer to the tumor periphery and the adjacent liver tissue." (PMID 27460820, 2016). "Several studies have also confirmed Zeb1 as a key Wnt target as well as identification of miR-802 as a potential tumour suppressor via NGS techniques." (PMID 27590724, 2016). "In most Oncomine data sets with lower tumour ZEB1, the expression levels of both EGFR and KRAS were marginally higher in tumours compared with paired normal lung tissues." (PMID 27456471, 2016). "MET-like changes in TE-8 ESCC cells mediated through ZEB1 degradation were able to inhibit tumorigenicity and tumor growth in a mouse xenograft model." (PMID 26784241, 2016). "To identify the potential underlying mechanisms for this effect, we subjected xenograft tumor tissues to Western blot analyses against p-AMPK, p-mTOR and mesenchymal phenotype-associated proteins (i.e., slug, vimentin, N-cadherin, and ZEB1)." (PMID 27223262, 2016). "We thus used IPTG‐inducible shRNA‐ZEB1 to evaluate the impact of ZEB1 knockdown on tumor shrinkage in established tumors." (PMID 27596438, 2016). "Herein we demonstrate that miR-200 loss dramatically sensitizes tumor cells to secondary activation by the ECM and investigated how the miR-200/Zeb1 axis controls the matrix-dependent tumor cell invasion and metastasis." (PMID 26728244, 2016). "As a crucial EMT inducer, ZEB1 not only promotes malignant progression, but is also necessary for the tumour‐initiating capacity of epithelial cancer cells." (PMID 27027258, 2016). "Zeb1 enhanced tumor-initiating properties of pancreatic and colorectal cancer cells by inhibiting the expression of stemness-repressing microRNAs (miRNAs) including miR-200 family and miR-203." (PMID 27840647, 2016).
tumor (continued). "Consistently, a recent study indicated that Zeb1 expression was positively accordant with tumor development and poor prognosis in ICC patients." (PMID 27655691, 2016). "Both in vitro and in vivo experiments demonstrated that hTERT promotes tumor invasion and metastasis via interactions with ZEB1." (PMID 26540342, 2016). "Zeb1 and Zeb2 have been shown to regulate the expression of various EMT- and tumor related genes and thereby have been implicated in EMT, tumorigenesis and metastasis." (PMID 27588490, 2016). "In VM‐positive malignant tumour cells, ZEB1 expression is higher compared with the VM‐negative tumour cells and the ZEB1 expression occurred concomitantly with features of EMT." (PMID 27027258, 2016). "Mechanisms by which Zeb1 regulates tumor progression, cancer stem cell properties, and chemoresistance are discussed in greater detail elsewhere and thus are not further summarized below." (PMID 27840647, 2016). "In the current study, we have additionally identified an important role for ZEB1 in tumor progression; ie, the stimulation of angiogenesis." (PMID 26882471, 2016). "We found that ZEB1 enhances tumor angiogenesis in vivo both in a Matrigel plug assay and in a nude mouse xenograft model." (PMID 26882471, 2016). "Results from previous studies have shown that ZEB1 plays an important role in regulating E-Cadherin expression in tumor invasion and metastasis, and its expression is closely related to the prognosis of cancer." (PMID 27285757, 2016). "As co‐expression of HIF‐1α, ZEB1 and decreased expression of E‐cadherin is considered as a significant marker to predict the invasion and migration capacity of malignant tumour cells." (PMID 27027258, 2016). "In order to explore further the mechanisms of EMT induction in the resistant tumours, we looked at expression of Zeb1, which is a known transcriptional regulator of EMT." (PMID 26721874, 2016). "Of note, tumor buds show strong expression of the epithelial-mesenchymal transition markers ZEB1 and ZEB2." (PMID 26716653, 2016). "Accelerating oncogenic KRAS expression is responsible for DDX3-induced tumor invasion via the β-catenin/zinc finger E-box binding homeobox 1 (ZEB1) axis." (PMID 27007150, 2016). "Such an effect promotes tumor progression and metastasis through the miR-200a-3p/ZEB1 signaling pathway." (PMID 27285757, 2016). "Previous studies have shown that ZEB1 plays an important role in regulating E-cadherin expression to tumor invasion and metastasis, and its expression is closely related to the prognosis of cancer patients." (PMID 26540342, 2016). "A novel aspect was a significant association between intestinal differentiation and reduced features of EMT (tumor budding, ZEB1 and E-Cadherin expression)." (PMID 26951071, 2016). "Upregulation of nuclear Zeb1 was seen only in the resistant spindle cell tumours, consistent with a Zeb1-regulated induction of EMT." (PMID 26721874, 2016). "Members of this family suppress tumor invasiveness and metastasis by inhibiting ZEB1 and ZEB2 initiated EMT." (PMID 27023622, 2016). "In contrast, all seven EGFR-mutated tumours had lower ZEB1 and the levels of ZEB1 were significantly lower in EGFR mutant tumours than that in EGFR wild-type tumours (Student's t-test P=0.027) or in KRAS mutant tumours (Student's t-test P=0.013)." (PMID 27456471, 2016). "The current understanding of the EMT process is that transcription factors including SNAI1, SNAI2, ZEB1, ZEB2 and TWIST1 down-regulate CDH1 expression which subsequently results in the loss of cell adhesion and migration of tumor cells." (PMID 26214683, 2015). "HMGA2, Twist1 and ZEB1 expressions were significantly higher in samples with poor prognosis with stage IV tumor expressing highest levels of HMGA2, Twist1 and ZEB1." (PMID 25868853, 2015). "Our data link high expression of miR-203—and low expression of ZEB1—to reduced tumor recurrence and metachronous metastasis after curative surgery and adjuvant chemotherapy." (PMID 25872941, 2015).
tumor (continued). "The in vivo results showed that the tumor growth and liver metastasis were remarkably retarded by both miR-652 overexpression and ZEB1 knockdown." (PMID 26498682, 2015). "We tested the expression of Zeb1 in the 105 NSCLCs, and found that Zeb1 expression in tumour samples was much higher than in paired normal lung tissues." (PMID 26395400, 2015). "Expression levels of the representative mesenchymal markers, vimentin and ZEB1, are increased, while expression of the epithelial marker E-cadherin was decreased in AR tumors compared to Br3CT tumor." (PMID 26336988, 2015). "The distinct function of miR-200a and miR-200b subfamilies on HCC cell growth and migration implied that miR-200b subfamily exerted its tumor suppressive functions via a mechanism beyond the inhibition of ZEB1/2 mediated EMT." (PMID 25909223, 2015). "At last, we found the decreased miR-652 and increased ZEB1 were also correlated to late tumor stage, lymphatic invasion and vascular infiltration." (PMID 26498682, 2015). "Since miR141 and miR200c share the same promoter and KLF8 strongly represses this promoter, it is likely that the regulation of miR200c and ZEB1 by KLF8 also contributes to the overall outcomes of the tumor progression." (PMID 26025929, 2015). "Elevated expression of EMT-inducers like ZEB1 enables tumor cells to detach from the primary tumor and invade into the surrounding tissue." (PMID 26334100, 2015). "In contrast, miR-33b knockdown or HMGA2, Twist1 or ZEB1 overexpression significantly attenuated the effect of cordycepin on lifespan of tumor-bearing mice." (PMID 25868853, 2015). "ZEB1 expression in pathologic specimens correlated with advanced tumor grade and worse outcomes and had an inverse relationship with E-cadherin." (PMID 25593307, 2015). "The immunohistochemistry and Western blot assays showed that both Zeb1 and Vimentin were down-regulated and E-Cadherin was up-regulated in tumours harvested from mice inoculated with the miR-144-A549-luciferase cells." (PMID 26395400, 2015). "miR141 is known to function as a tumor suppressor by repressing ZEB1, one of the strong EMT inducers." (PMID 26025929, 2015). "HIF-1α and ZEB1 are both widely considered as tumor-initiating factors, but our results demonstrate that ZEB1 is a direct downstream of HIF-1α, suggesting a novel molecular mechanism for HIF-1α-inducing EMT and cancer metastasis." (PMID 26057751, 2015). "The aberrant expression of epithelial-mesenchymal transition (EMT) transcription factors, such as ZEB1 (zinc finger E-box binding homeobox 1), can facilitate both neoplastic transformation and tumor cell dissemination." (PMID 25537510, 2015). "Ets1 also induces expression of the epithelial-mesenchymal transition (EMT) transcription factor Zeb1, and thereby links Ras mutation to EMT, which is thought to drive tumor invasion." (PMID 25880398, 2015). "We next performed the multivariate regression analysis controlling for sex and tumor grade and found that both ZEB1 (p = 2.2 × 10−7) and ZEB2 (p = 0.006) were significantly associated with the expression levels of CD36 in the human protein samples." (PMID 26424075, 2015). "Previous studies in tumor cells revealed that a HIF-1α-ZEB1 signaling is involved in hypoxia-induced EMT." (PMID 26819949, 2015). "Emerging evidences suggest that many EMT-inducing transcription factors such as Snail and ZEB1 have been found to be associated with expression of FOXM1, which leads to tumor aggressiveness and metastasis." (PMID 25935853, 2015). "MiR-200s have been demonstrated to act as a tumor suppressor by suppressing Zinc-finger enhancing binding transcription factors (ZEB1 and ZEB2) to increase the E-cadherin in cancer cells." (PMID 24918286, 2014). "Our data represents the first attempt to improve the tumor vaccine B16F10/GPI-IL-21 efficacy in combination with miR200c overexpression or ZEB1 knockdown in B16F10 cells." (PMID 24625224, 2014).